RAD50 (RAD50 double strand break repair protein)
Diseases named in the same sentence as RAD50 in open-access papers (continued):
Sharing a sentence is not in itself a finding about the gene and the disease.
ovarian carcinoma (continued). "RAD50 depletion in ovarian cancer cell lines also increased response to PARP inhibitor therapy." (PMID 35006434, 2020). "In addition, as RAD50 is multi-functional protein with previously reported interacting partners, we conducted a bioinformatic analyses to understand RAD50 interactome in ovarian cancer cells." (PMID 35006434, 2020). "Interestingly, a link between RAD50 deficiency, BRCAness phenotype and PARP inhibitor sensitivity has been shown in ovarian cancers." (PMID 35006434, 2020). "RAD50 expression-based stratification and personalization could be viable clinical strategy in ovarian cancers." (PMID 35006434, 2020). "We hypothesized that these mechanisms could play a role in CX3CR1-dependent downregulation of RAD50 in ovarian cancer cells." (PMID 29712888, 2018). "We then postulated that Rad50 may activate NF‐κB pathway in ovarian cancer." (PMID 34734468, 2021). "In ovarian cancer cell lines, however, RAD50 variants have not been described previously." (PMID 35006434, 2020). "We hypothesised a role for RAD50 in ovarian cancer pathogenesis and therapeutics." (PMID 35006434, 2020). "We provided evidence that Rad50 ectopic expression promotes migration/invasion and induces EMT in ovarian cancer cells." (PMID 34734468, 2021). "Future studies will be required to explore the molecular cooperation between Rad50 and CARD9 in promoting proliferation/invasion and inducing EMT in ovarian cancer." (PMID 34734468, 2021). "Sub-cellular localization of RAD50 at baseline and following cisplatin therapy was tested in platinum resistant (A2780cis, PEO4) and sensitive (A2780, PEO1) ovarian cancer cells." (PMID 35006434, 2020). "The relevance of other homologous recombination repair proteins, e.g. MRE11, RAD50, NBS1 (MRN complex) in ovarian carcinomas is unclear." (PMID 28073364, 2017). "In addition to facilitating SIK2 degradation, this compound decreases RAD50 phosphorylation, impairs the nuclear translocation of RAD50, and when used with PARP inhibitors, has a synergistic cytotoxic effect on ovarian cancer." (PMID 40612876, 2025). "The MRN complex (MRE11, RAD50, and NBN) is implicated in nonhomologous end joining DNA repair and has rarely been reported in association with ovarian cancer." (PMID 35159349, 2022). "Because higher level of Rad50 in HGSOC patients was significantly related to metastasis, we hypothesized that Rad50 promotes invasion capacity of ovarian cancer cells." (PMID 34734468, 2021). "In addition, ectopic expression of Rad50 promoted proliferation/invasion and induced EMT of ovarian cancer cells, whereas knockdown of Rad50 led to decreased aggressive behaviors." (PMID 34734468, 2021). "In high-grade ovarian cancer, high expression of NBS1 and RAD50 correlates with improved outcome." (PMID 31767017, 2019). "CARD9 was detected in the immunoprecipitates with anti‐Rad50 antibody, but not with the control mouse IgG in HEK293T and ovarian cancer cell lines." (PMID 34734468, 2021). "The objective of this study was to investigate the prevalence of lack of MRE11, RAD50, NBS1 protein detection in epithelial ovarian cancer (EOC)." (PMID 28073364, 2017). "Frequent lack of MRE11, RAD50, NBS1 protein detection in type I human ovarian carcinomas is observed in EOC and our data suggests further investigation regarding sensitivity to PARP-inhibition in tumours lacking MRE11 expression." (PMID 28073364, 2017).
Nijmegen breakage syndrome (20 papers, 2013 to 2023). Nijmegen breakage syndrome is a rare genetic disease presenting at birth with microcephaly, dysmorphic facial features, becoming more noticeable with age, growth delay, and later-onset complications such as malignancies and infections. "In this case, Nijmegen breakage syndrome carrier status caused by RAD50 heterozygous mutation and previous bevacizumab therapy could be the predisposing factor for cutaneous metastases." (PMID 37920167, 2023). "We hypothesized that the defective PKA functional sites may also lead to Nijmegen breakage syndrome associated with neurological phenotype in Rad50 mutations, however this potential phosphorylation sites remain to be validated." (PMID 32509463, 2020). "A variety of primary immunodeficiencies and congenital BM failure syndromes (predominantly with DNA repair impairment), including Nijmegen breakage syndrome, Ligase 4, Cernunnos, Rad50 deficiencies, Fanconi anemia, and some others, combine the symptoms of microcephaly and cytopenia." (PMID 31053147, 2019). "Clearly the MRN complex plays a very important role in ATM function, particularly considering the similarity in clinical phenotypes of patients lacking ATM (A-T) compared with patients expressing hypomorphic alleles of MRE11 or RAD50 (A-T-like Disorder) or Nbs1 (Nijmegen Breakage Syndrome)." (PMID 23525106, 2013). "Mutations in NBS1/NBN and RAD50, respectively, cause Nijmegen breakage syndrome (NBS) and an NBS-like disorder, with consequent microcephaly, but only the former suffers from immunodeficiency." (PMID 34502215, 2021). "Mutations in MRE11, RAD50, and NBS1 cause human genomic instability syndromes Ataxia-Telangiectasia-like disorder (A-TLD), NBS-like disorder (NBSLD), and Nijmegen Breakage Syndrome (NBS), respectively." (PMID 35153719, 2021). "The common mutation in NBS1 (657del5) causing Nijmegen breakage syndrome impairs NBS1 interaction with MRE11 and RAD50." (PMID 29973640, 2018). "These include the clinically similar Ataxia telangiectasia (AT), AT like disease (ATLD), Nijmegen Breakage Syndrome (NBS) and NBS like disorder (NBSLD), caused by mutations in the ATM, MRE11, NBS1 and RAD50 genes respectively." (PMID 26160886, 2015). "In humans, homozygous hypomorphic mutations in MRE11, NBN (coding for the NBS1 protein) and RAD50 genes cause ataxia telangiectasia‐like disorder (ATLD‐OMIM:604391), Nijmegen breakage syndrome (NBS‐OMIM:251260) and NBS‐like disorder (NBSLD‐OMIM:613078), respectively." (PMID 35839783, 2022). "Ataxia-telangiectasia (A-T, ATM mutation), the related A-T like disease (ATLD, MRE11 mutation), Nijmegen breakage syndrome (NBS, NBS1/NBN mutation) and the more recently identified NBS like disease (NBSLD, RAD50 mutation), all present with similar pathological outcomes in humans." (PMID 23532176, 2013). "When mutated, diseases such as Nijmegen breakage syndrome (NBS) and the hereditary cancer syndrome variant Li-Fraumeni (CHK2) will be developed suggesting the importance of these conserved residues within Rad50 for DNA repair and maintenance." (PMID 32509463, 2020). "Hypomorphic, biallelic mutations in the MRE11, RAD50 and NBN genes are linked to recessive genetic conditions, ataxia telangiectasia like disorder (AT-LD), NBS-like and Nijmegen breakage Syndrome (NBS), respectively, some of which are characterized by increased risk of cancer." (PMID 24093751, 2013).
asthma (16 papers, 2008 to 2025). "We carried out a case-control study to assess the role of the asthma susceptibility SNP variants (rs2244012 and rs6871536) of the RAD50 gene, as predicted by GWAS, in relation to asthma pathogenesis within a scarcely studied Pakistani population." (PMID 41001556, 2025). "This case-control study aimed to investigate the association of two Single nucleotide polymorphisms (SNPs) rs2244012, and rs6871536 of RAD50 with asthma susceptibility using experimental and computational tools." (PMID 41001556, 2025). "In this study, the alternative allele “G” of RAD50′s rs2244012 showed a significant association with asthma in the allelic model (P = 0.0014)." (PMID 41001556, 2025). "Genome-wide association studies (GWAS) have indicated that several single nucleotide variants (SNVs) of the RAD50 gene are significantly associated with childhood-onset asthma." (PMID 41001556, 2025). "Within RAD50, rs6871536 was identified as potentially associated with asthma (OR = 1.44, P = 1.7 × 10 – 9)." (PMID 41001556, 2025). "the rs2244012, and rs6871536 variants of RAD50 gene are significantly association with childhood asthma in Pakistan." (PMID 41001556, 2025). "The role of RAD50 rs6871536 in childhood asthma predisposition was also validated in Chinese population." (PMID 33925009, 2021). "Polymorphisms within the RAD50 gene on chromosome 5q31 were consistently associated with IgE levels (P values 6.28×10−7−4.46×10−8) and increased the risk for atopic eczema and asthma." (PMID 18846228, 2008). "In these cohorts we observed weak associations of RAD50 variants with eczema (P = 0.007–0.01) and with asthma (P = 0.017–0.002)." (PMID 18846228, 2008). "Despite limited evidence regarding the gene expression of RAD50 in airways and its direct association with asthma, genome wide association studies (GWAS) and candidate gene studies have identified genomic variants of this gene as being significantly linked to the disease." (PMID 41001556, 2025). "RAD50 is a plausible candidate gene implicated in asthma pathogenesis." (PMID 41001556, 2025). "The first study to investigate the correlation between RAD50 and asthma exacerbation was conducted on the COPSAC cohort highlighting a genome-wide significant association between RAD50 rs6871536 polymorphism and early-onset asthma with recurrent and severe exacerbations." (PMID 33925009, 2021). "Therefore, RAD50 represents a promising new susceptibility gene for asthma exacerbations, although replication of these results would require more studies, in order to overcome genetic heterogeneity and environmental influences among different populations." (PMID 33925009, 2021). "However, the biological role of RAD50, and its genomic variants that predispose individuals to asthma, remains unclear." (PMID 41001556, 2025). "Several genes within the cytokine gene cluster on chromosome 5, specifically IL3, IL4, CSF2, TSLP, IL5, RAD50, and IL13, are recognized as potential asthma susceptibility genes due to their roles in inflammatory regulation among sensitized asthma patients." (PMID 41001556, 2025). "These were in loci previously associated with asthma exacerbations (GSDMB, RAD50, HLA‐DQB1, ADAM33, VDR, and CDHR3) or moderate‐to‐severe asthma (IKZF3, TSLP, MUC5AC, C11orf30, SMAD3, and WDR36)." (PMID 35754128, 2022). "RAD50 promotes the development of asthma by inducing inflammatory factors secreted by Th2 cell, and it was found to be associated with hay fever." (PMID 32373153, 2020). "Notably, the SNP rs2244012 in the RAD50 gene, in conjunction with the rs1063355 SNP in the HLA-DQB1 region, exhibited a strong association with asthma." (PMID 41001556, 2025). "In addition, we genotyped four SNPs that have been reported to be associated with asthma, rs7216389 in ORMDL3, rs11684634 in PDE11A, rs1544791 in PDE4D and rs2706347 in RAD50." (PMID 23046476, 2012).
asthma (continued). "On the contrary, more recent case-control study on 652 Northeastern Han Chinese asthmatic children did not report significant association between two RAD50 SNPs (rs2244012 and rs6871536) and pediatric asthma risk, questioning the effective role of this gene in this specific subpopulation." (PMID 33925009, 2021). "We focused on genes related to Th2 response, and found that the Rad50 HS 5 (RHS V) within the Th2 cytokine LCR had significantly reduced accessibility in Bcl11b-deficient T-helper cells compared to WT cells from asthma-induced mice, despite the fact that Bcl11b did not bind to this region." (PMID 29700302, 2018). "Although its possible role in asthma is unknown, the product of the gene, similarly of some earlier found asthma genes (e.g. RAD50) plays a role in DNA repair, thus theoretically its altered function might influence the resistance of the cells to environmental stress." (PMID 22432035, 2012). "Even though the expression of this protein is relatively low in most tissues, making its direct function related to asthma unclear, the MRN complex (comprising MRE11, RAD50, and NBS1) plays a role in the somatic hypermutation and gene conversion of the immunoglobulin region." (PMID 41001556, 2025). "DNA Repair Protein RAD50 gene (RAD50) is involved in DNA double-strand break repair and its direct role in asthma is not completely clarified." (PMID 33925009, 2021).
NBS-like disorder (13 papers, 2015 to 2026). "Similarly, mutations within RAD50 result in a genetic disorder that clinically presents with neurological developmental defects, resulting in the designation as NBS-like disorder (NBSLD; OMIM accession #613078)." (PMID 36358700, 2022). "A very similar phenotype to NBS was seen in patients with Nijmegen Breakage Syndrome-like Disorder (NBSLD – OMIM:613,078) caused by defects in the RAD50 gene (ID:10,111, MIM:604,040)." (PMID 28376765, 2017). "It is unlikely transformed cells can survive without MRE11A, RAD50, ATRIP or PALB2 although significantly reduced levels may be tolerated, as evidenced by the ATR expression in Seckel syndrome and hypomorphic MRE11A and RAD50 mutations in ATLD and NBS-like disorder patients, respectively." (PMID 26438152, 2015).
Fanconi anemia (12 papers, 2011 to 2025). Fanconi anemia (FA) is a hereditary DNA repair disorder characterized by progressive pancytopenia with bone marrow failure, variable congenital malformations and predisposition to develop hematological or solid tumors. "There are numerous genes involved in the DDR pathway, and several studies suggest that platinum therapy may benefit patients with mutations in genes such as ATM and ATR, those within the MRN complex (e.g., RAD50), and Fanconi anemia core genes." (PMID 39860372, 2025). "HRR alterations involve Fanconi anemia genes (PALB2, FANCA, FANCL, FANCI, FANCC), core RAD genes (RAD50, RAD51, RAD51B, RAD51C) as well as DNA damage response genes (ATM, ATR, CHEK1, CHEK2)." (PMID 36531003, 2022). "These genes include the Fanconi anemia pathway genes: FANCA, PALB2, BRIP1, RAD51C and XRCC2 and non-Fanconi anemia genes: ATM, CHEK2, NBN, RAD50, RAD51B, and RAD51D." (PMID 28202063, 2017).
prostate carcinoma (12 papers, 2011 to 2024). A carcinoma that arises from epithelial cells of the prostate gland. "When repeating analyses for pathogenic variants in four additional genes (BRCA1, RAD50, MLH1, and MSH6) with weaker evidence of association with prostate cancer risk, the risk modifying effect of PRS was similar, albeit the associations were diminished." (PMID 38014910, 2023). "Knockdown of SMYD3 caused differentially expressed DNA repair genes RAD50 and RAD51 in prostate cancer cells." (PMID 28630472, 2017). "As an example, we predicted that RAD50 with TRF2 have prostate cancer specific interaction that turned out to be having validation from the literature." (PMID 21777411, 2011). "Xu analyzed 80 prostate cancer patients as well as 351 prostate cancer patients from The Cancer Genome Atlas (TCGA) and found that abnormal Rad50 gene expression correlated significantly with the invasive progression and low survival rate of this type of cancer." (PMID 34215272, 2021). "APE2 did not have a significant relationship with Mre11 or Rad50 in uterine nor prostate cancers." (PMID 32111912, 2020). "The original prostate cancer study indicated that the 14 prostate cancer samples harbored 38 tumor-specific chimeric transcripts, of which at least 5 are recurrent transcripts in Chinese population, including TMPRSS2-ERG, USP9Y-TTTY15, CTAGE5-KHDRBS3, RAD50-PDLIM4, and SDK1-AMACR." (PMID 29181411, 2017).
colorectal cancer (11 papers, 2013 to 2026). A primary or metastatic malignant neoplasm that affects the colon or rectum. "In gastric cancer, colorectal cancer and rectal cancers, similarly, high RAD50 has been associated with poor clinical outcomes in patients." (PMID 35006434, 2020). "Elevated RAD50 was associated with poor patient survival, and experimentally knocking out RAD50 increased sensitivity to irradiation in colorectal cancer." (PMID 30769804, 2019). "Microsatellite stability was not ascertained for specimens in this study, which may explain the disparate results, as Gao and colleagues found that clinical outcomes associated with low RAD50 expression were specific for microsatellite stable colorectal cancers." (PMID 30769804, 2019). "Survival analysis of differentially expressed longevity-related genes in colorectal cancer found that the expression of 18 genes, including RAD50, ELOVL6, and BEND3, had a greater impact on patient survival." (PMID 40426913, 2025). "This strategy turned out to be successful given that we were able to validate endogenous interactions of P2-HNF4α with PARP1, RAD50 and DNA-PKcs in colorectal cancer cell lines." (PMID 31060309, 2019). "Several of these proteins including PARP1, RAD50, and DNA-PKcs were confirmed to interact with HNF4α in colorectal cancer cell lines." (PMID 31060309, 2019). "Furthermore, advanced colorectal cancers with MSI are more sensitive to irinotecan, and low MRE11 or RAD50 expression in these tumours is associated with increased chemosensitivity, and predicts better outcomes." (PMID 30769804, 2019). "Several studies have confirmed defective MRE11 expression in MSI colorectal cancers, and interestingly, a mild defect in either MRE11 or RAD50 is adequate to downregulate RAD50 and overall MRN expression in MSI tumours." (PMID 30769804, 2019).
lung carcinoma (11 papers, 2014 to 2024). "We assessed the endogenous radioresistance levels of lung cancer cells by colony formation assays and compared them with the phosphorylation levels of RAD50 and ATM, key components of the DDR activation after radiation." (PMID 39408794, 2024). "Whereas another study that examined RAD50 reported that upregulation of RAD50 had the strongest correlation with radioresistance in lung cancer patients." (PMID 37474724, 2023). "Strong evidence for two deleterious germline mutations (rs587781454 in RAD50 and rs756875895 in MAX) has been shown in lung cancer patients." (PMID 34540367, 2021).
microcephaly (10 papers, 2013 to 2026). A congenital or acquired developmental disorder in which the circumference of the head is smaller than normal for the person's age and sex. "RAD50 deficiency causes a genomic instability disorder characterized by microcephaly and stunted growth." (PMID 41031707, 2025). "Human RAD50 deficiency is a very rare autosomal recessive genomic instability disorder characterized by microcephaly and stunted growth." (PMID 41031707, 2025). "Neurological defects, including microcephaly, ataxia or neurodegeneration, are a hallmark for autosomal recessive mutations in individual genes encoding components of the Mre11/Rad50/Nbs1 (MRN) complex." (PMID 30584599, 2018). "It remains mechanistically unclear why mutations in MRE11 result in neurodegeneration, similar to what is observed in A-T patients, while other mutations in NBS1 or RAD50 cause microcephaly." (PMID 23532176, 2013). "More recently, ATLD patients with microcephaly, rather than neurodegeneration, have been identified as well as NBSLD patients with microcephaly due to RAD50 mutations." (PMID 23532176, 2013). "Rad50 mutations can lead to microcephaly, mental retardation and growth retardation in human." (PMID 32509463, 2020).